EGFR (epidermal growth factor receptor)
Diseases named in the same sentence as EGFR in open-access papers (continued):
Sharing a sentence is not in itself a finding about the gene and the disease.
Skin rash (continued). "In our results, patients with EGFR inhibitor induced skin rash had lower expression of miR-520e indicating a better prognosis, and this was especially significant in patients treated with monoclonal antibodies." (PMID 34012511, 2021). "Rash severity has been positively correlated with the clinical outcomes of EGFR inhibitor administration in several cancer types." (PMID 34441007, 2021). "Dermatologic toxicities are commonly observed among mCRC patients who are treated with anti-EGFR therapies, with 79% of Vectibix users in the current study reporting they experienced a rash in response to treatment." (PMID 33973081, 2021). "Our results suggest that the QoL is negatively affected for those patients currently experiencing an anti-EGFR rash." (PMID 33973081, 2021). "Among the G3–G4 AEs, diarrhea was more frequent in the 5FU/LV cohort (9.1%), while skin rash was more frequent in the 5FU/LV+anti-EGFR and anti-EGFR cohorts (8.5% and 9.1%, respectively)." (PMID 34778029, 2021). "Previous studies have revealed that the most common adverse effects of EGFR-TKI therapy are skin rashes (31.4%), diarrhea (14.2%), pruritus (6.7%), and hepatic toxicity (3.8%)." (PMID 33489880, 2020). "The occurrence rate of skin rash due to erlotinib, an EGFR inhibitor used clinically to treat various cancers, is extremely high (50%) compared with that due to gefitinib, another EGFR inhibitor (10%)." (PMID 30868372, 2019). "The WoMo score represents a sensitive tool for studies exploiting treatments against EGFR mediated acne‐like skin rash." (PMID 31199595, 2019). "In contrast, skin rash severity is positively correlated with clinical response and predicts the efficacy of EGFR-targeting therapies." (PMID 31703435, 2019). "The most common adverse events (AEs) of these three major EGFR-TKIs include skin rash, stomatitis, paronychia, and diarrhea, which are manageable with treatment interruptions or dose reduction and best supportive care." (PMID 29849936, 2018). "Skin rash, another well-documented adverse effect of anti-EGFR MoAs, is reportedly predictive of better clinical benefits in mCRC patients." (PMID 29391418, 2018). "This suggests that LY3164530 effectively inhibits EGFR since skin rash is a known pharmacodynamic marker of EGFR inhibition." (PMID 29926131, 2018). "The development of skin rashes is the most common adverse event observed in cancer patients treated with epidermal growth factor receptor-tyrosine kinase inhibitors such as erlotinib." (PMID 29719624, 2018). "In this meta-analysis, the addition of an anti-EGFR agent significantly increased some grade 3/4 AEs including diarrhea, mucositis, and skin rash." (PMID 29228748, 2017). "But in NSCLC patients, they are only potent agents to mutant EGFR instead of EGFR T790M, because the suppression of WT EGFR leads to dose-limiting toxicity, such as skin rash/acne, paronychia, and diarrhea." (PMID 29163853, 2017). "Skin rash and diarrhea are the most frequent ADRs in patients receiving EGFR TKIs, and several meta-analyses have reported a significantly higher risk of skin rash with afatinib (84.8%) than with erlotinib (62.0%) or gefitinib (62.0%) (p < 0.01)." (PMID 29237484, 2017). "Patients receiving EGFR antibody therapy often experience skin rashes in areas rich in pilosebaceous units." (PMID 28292888, 2017). "Such a mutation leads to an EGFR-independent activation of the MAPK pathway, rendering EGFRIs ineffective and making it surprising that EGFRI-induced rash was still associated with OS." (PMID 28456787, 2017). "The type and distribution of the skin rash were different from the acneiform rash that is observed in patients treated with 1G/2G EGFR-TKIs." (PMID 27912760, 2016). "The most common adverse events in EGFR-TKIs group were skin rash followed by diarrhea, cutaneous pruritus and dry skin." (PMID 26624882, 2016).
Skin rash (continued). "Acneiform skin rash occurs up to 70–80% of patients during the course of therapy with EGFR inhibitors, and can be treated with topical steroid and antibiotics." (PMID 27467256, 2016). "Between 50% and 100% of patients treated with anti-EGFR antibodies display various skin rashes, while diarrhea is the most common dose-limiting toxicity in patients treated with EGFR TKI." (PMID 27153091, 2016). "A four-genes model (rs884225 in EGFR 3′UTR, rs7787082 in ABCB1 intron, rs38845 in MET intron and rs3803300 in AKT1 5′UTR) was associated with TKIs induced ADRs and skin rash." (PMID 26988277, 2016). "Earlier steroid treatments for skin toxicities and even pre-emptive regimens have been effective in reducing EGFR TKI-related rash." (PMID 26499382, 2016). "By contrast, the most common adverse events in EGFR-TKIs plus bisphosphonates group were skin rash, cutaneous pruritus, diarrhea and liver dysfunction." (PMID 26624882, 2016). "In summary, the development of 3G EGFR-TKIs is encouraging because they have often shown noteworthy effectiveness and reduced rates of classic AEs, such as diarrhea and skin rash." (PMID 27912760, 2016). "In the clinic, skin rash, interstitial pneumonia, or diarrhea are common or life threatening side effect of EGFR-TKIs." (PMID 26515464, 2015). "Rash development has been associated with EGFR-TKI efficacy in NSCLC, and a meta-analysis previously showed that a skin rash was an independent predictive factor for progression and survival in EGFR TKI-treated NSCLC patients." (PMID 25120716, 2014). "This narrative review will focus on the reactive and prophylactic approaches, for the improved management of the cutaneous toxicities, specifically rash, induced by EGFR-targeted agents, investigated in recent randomized clinical trials." (PMID 23801914, 2013). "EGFR-TKIs are thought to affect basal keratinocytes, leading to the development of skin rash side effects." (PMID 23383079, 2013). "Vitamin K cream was also identified as having a potential role in the management EGFR-targeted agent induced rash." (PMID 23801914, 2013). "Common side effects of EGFR inhibitors include skin rash, hypomagnesemia, paronychia, fatigue, abdominal pain, nausea and diarrhea." (PMID 24795806, 2013). "Thus, skin rash in response to EGFR-TKI therapy may be an outward manifestation of the EGFR-TKI therapeutic effect on tumors, which may be explained by an association between skin rash and the EGFR-TKI efficiency even for the PFS and OS of patients from a molecular pathology perspective." (PMID 23383079, 2013). "Skin rash is a main side effect of EGFR-TKI therapy and occur in approximately two-thirds of patients with NSCLC." (PMID 23383079, 2013). "Skin rash is notorious as an adverse event of EGFR-TKI and is noted in up to two-thirds of patients receiving any of these agents although severe in only 5 to 10%." (PMID 23420789, 2013). "By the occurrence of a severe exanthema, pause or dose reduction of the EGFR inhibitor can be considered." (PMID 23918349, 2013). "Usually, it takes up to 2 or 3 weeks after the first intake of the EGFR inhibitor until the first signs of exanthema." (PMID 23918349, 2013). "The prophylactic application of oral antibiotics (tetracycline or minocycline) alone was effective for the early phase of the exanthema during the first month of anti-EGFR treatment." (PMID 23918349, 2013). "Prospective studies are needed to increase our understanding of the biological mechanism linking rash and erlotinib benefit, including dose-escalation studies or studies of the relation between rash and tumour EGFR copy number." (PMID 23078958, 2012). "EGFR inhibitor-related rash occurs very frequently in the prescribed patients, usually starting within two to three days following initiation of EGFRI treatment, and worsen within one to three weeks." (PMID 22997576, 2012).
Skin rash (continued). "Among patients with wild-type EGFR who were assigned erlotinib and developed rash (n=94), HR for overall survival was 0·86 (95% CI 0·66–1·12, p=0·27) and for progression-free survival was 0·69 (0·53–0·90, p=0·0070)." (PMID 23078958, 2012). "Since this skin rash follows from the inhibition of epidermal cells expressing normal levels of the EGFR, using the rash as a marker of drug activity and clinical outcome was proposed and our theoretical study supports this." (PMID 22399130, 2012). "The predominant view is that the clinical efficacy of EGFR antagonists correlates with skin rash toxicity, as documented for most EGFR-targeted agents, and induction of objective clinical response." (PMID 24212794, 2011). "Except for ILD, the most adverse effects of EGFR-TKIs are skin rashes and diarrhea, which can be tolerated and are manageable." (PMID 24212826, 2011). "The predominant view is that the efficacy of EGFR antagonists correlates with skin rash toxicity and induction of objective clinical response." (PMID 24212794, 2011). "The most frequently reported side effect of EGFR inhibitors is a dose-dependent acneiform skin rash occurring in more than 50% of patients." (PMID 21283802, 2011). "The majority of patients treated with a MoAb EGFR inhibitor will experience dermatological side effects, most notably the papulopustular skin rash, which can impact quality of life and affect adherence to therapy." (PMID 20680104, 2010). "Given thateven mild–to–moderate skin rash can result in significant patient distress and impairment, theclinical benefit of anti–EGFR therapy must be carefully weighed against the toxicity of this commonside effect." (PMID 20302205, 2010). "Currently identified side effects of the various anti-EGFR therapies include skin rash due to the changes in keratinocyte and hair follicle maturation, interstitial lung disease and other respiratory problems." (PMID 21151926, 2010). "In termsof clinical predictors of response, the development of skin rash has been suggested as a surrogate markerof favorable response to EGFR inhibition." (PMID 20302205, 2010). "Long before KRAS emerged as a predictive marker for responsiveness to EGFR monoclonal antibody targeted therapy, it was well known that skin rash was a very good surrogate marker for responsiveness to EGFR targeted therapies." (PMID 19386128, 2009). "Rash is a common adverse effect of EGFR inhibitors and occurs in approximately 45%–100% of patients." (PMID 19636422, 2009). "The skin rash by EGFRI is thought to be the direct consequence of the EGFR blockade in basal epidermal keratinocytes as well as the outer root sheath of hair follicles, leading to a local growth arrest and consecutive inflammation." (PMID 18226196, 2008). "There was no clear association between treatment duration and any of the following: PS (P=0.262), histology (P=0.751), disease stage (P=0.103), smoking status (P=0.950), sex (P=0.663) and skin rash (P=0.357) and EGFR expression by IHC (P=0.254)." (PMID 18000506, 2007). "As is typical of erlotinib and other EGFR inhibitors, skin rash and diarrhoea were the most common side effects." (PMID 16570047, 2006). "Skin rash and diarrhea are the most common side effects in patients treated with EGFR-directed therapies." (PMID 16306877, 2006). "Skin rash occurs when EGFR signaling is blocked with either antibodies or small molecule inhibitors." (PMID 16306877, 2006). "However, skin rashes induced by EGFR-TKIs are the most common and earliest form of skin toxicity, often affecting the quality of life and treatment compliance of patients and leading to early discontinuation of therapy." (PMID 41570298, 2026). "Therefore, suppression of the inflammatory response is necessary for the management of EGFR inhibitor-induced skin rash." (PMID 40888993, 2025).
Skin rash (continued). "In this regard, a positive correlation between cetuximab (Cmab) skin rash and tumor response rate and survival has been reported, and it is considered that the incidence and severity of skin rash is closely related to the efficacy of anti-EGFR antibody." (PMID 39696667, 2024). "Skin rashes, which are a side effect of using EGFR-TKIs, can be relieved by TC." (PMID 39170692, 2024). "However, although EGFR inhibitors generate strong anti-cancer effects, they often induce skin rashes, which substantially affect quality of life and impact medication adherence." (PMID 38092882, 2023). "Secondly, previous studies revealed that platelet activation could be triggered by EGFR-TKI treatment and low-dose aspirin treatment is effective on EGFR-TKI-induced skin rashes." (PMID 36872336, 2023). "Additionally, the mechanism of action of vitamin K on EGFR inhibitor-induced skin rashes remains to be elucidated." (PMID 38092882, 2023). "Skin rash is common among patients treated with EGFR inhibitors, and the severity of skin rash may correlate with the efficacy of the treatment." (PMID 36165327, 2022). "Given that skin toxicity, which is a host response to EGFR inhibition, has a prognostic value in patients treated with EGFR inhibitors, we showed a significant correlation between serum IL-8 concentrations and the severity of skin rash (p = 0.0341)." (PMID 36269747, 2022). "To investigate whether dWAT responses to EGFR inhibition, we established a rat rash model by repeated oral gavage of Afatinib (Afa), an EGFR inhibitor with a high occurrence of skin toxicity." (PMID 35324426, 2022). "The anti-anaerobic and particularly anti-Fusobacterium activity of doxycycline could bring a potential benefit for patients with mCRC under EGFR inhibitors receiving this antibiotic agent for skin rashes." (PMID 34362003, 2021). "Hence, targeting EGFR often results in several adverse effects, including skin rashes, diarrhea, and lethargy." (PMID 33540470, 2021). "Rash is usually considered to be an EGFR-related toxicity in patients receiving BTKis." (PMID 33777941, 2021). "Thus, in these cancer entities patients presenting with a skin rash under EGFR inhibitor therapy are encouraged to continue this treatment with the prospect of an increased probability of a favorable treatment outcome." (PMID 34109122, 2021). "The tissue concentrations of EGF and EGF receptors are regulated by sex hormones such as estrogen and testosterone, which may contribute to sex differences in the development of skin rashes induced by anti-EGFR antibodies." (PMID 34441007, 2021). "Taking all this together, it makes it quite interesting to further investigate the role of miR-21, miR-31 and miR-520e for the development of EGFR inhibitor induced skin rash in patients treated with monoclonal antibodies and to understand possible mechanisms behind it." (PMID 34012511, 2021). "Indeed, a possible involvement of other stimuli in addition to EGFR inhibition are suggested in skin rash development of a mouse model." (PMID 31805013, 2020). "Therefore, for better clinical outcomes, especially for potential high responders with severe symptoms, it is important to control the emergence and severity of skin rash during EGFR-targeting therapies." (PMID 31703435, 2019). "Diarrhea and skin rashes are the most frequent adverse effects related with EGFR-TKI toxicity." (PMID 31417660, 2019). "In keeping with this hypothesis, correlations between skin rash and clinical benefit have been reported in connection with anti-epidermal growth factor receptor (EGFR) antibody, tyrosine kinase inhibitors, and capecitabine." (PMID 29882080, 2018). "Although the skin rash is the most common and cumbersome adverse effect of EGFR-TKI, it remains unknown if drug delivery and accumulation in the skin directly contributes to inflammation." (PMID 29719624, 2018).
Skin rash (continued). "Both ARCHER 1028 and ARCHER 1009 trials showed that on target adverse events related to the inhibition of EGFR WT in normal tissues were significantly increased with dacomitinib compared to erlotinib, mainly skin rash, paronychia, and gastrointestinal toxicities." (PMID 28424775, 2017). "In the clinic, skin rashes and diarrhea are common or life-threatening side effects of EGFR-TKIs." (PMID 29285266, 2017). "Epidermal growth factor receptor (EGFR) Tyrosine kinase inhibitor (TKI) is an effective targeted therapy for advanced non-small cell lung cancer (NSCLC) but also causes adverse drug reactions (ADRs) e.g., skin rash and diarrhea." (PMID 26988277, 2016). "Patients with EGFR mutations did not have a significantly different rate of skin rash than patients without EGFR mutations (73% vs. 50%; P = 0.118)." (PMID 26046796, 2015). "Despite the negative EGFR mutational test and only a mild and transient skin rash, the clinical efficacy of the TKI continued for several months keeping a complete response." (PMID 24661457, 2014). "EGFR mutation-negative patients who presented with a skin rash had significantly prolonged survival compared with those without a skin rash." (PMID 23420613, 2013). "skin rash after EGFR-TKI treatment may be an efficient clinical marker for predicting the response of patients with NSCLC to EGFR-TKIs." (PMID 23383079, 2013). "The clinical similarity between classical acne and an EGFR inhibitor-induced skin exanthema suggests that this medication might be successfully used for prevention or treatment of drug-induced exanthemas." (PMID 23918349, 2013). "Diarrhoea and skin rash were lower than previously reported with combination oxaliplatin, fluoropyrimidine, and EGFR antibody therapy, probably because only 31% received panitumumab—the panitumumab comparison is still masked—and also because of the short (6-week) duration preoperative treatment." (PMID 23017669, 2012). "Skin rash is the principal toxicity of both small molecule and antibody therapeutics targeting the epidermal growth factor receptor (EGFR), and retrospective analyses of a wide variety of studies have suggested that skin toxicity correlates with clinical benefit." (PMID 21878940, 2011). "The only grade 3 toxicity was a typical EGFR-related skin rash." (PMID 20961434, 2010). "The correlation between rash and response to the anti-EGFR treatment suggests that treatment response might be optimized by increasing the dose until the appearance of rash." (PMID 20680104, 2010). "Regarding treatment tolerance, the only grade 3 toxicity (National Cancer Institute Common Terminology Criteria, version 3.0) has been an EGFR-related skin rash on the face, chest and back that has responded well to oral doxycycline and topical clindamycin cream." (PMID 20961434, 2010). "Therefore, we hypothesized that adequate MKH delivery to the skin may suppress EGFR inhibitor-induced skin rashes." (PMID 38092882, 2023). "Consequently, it may be hypothesized that patients with long-term antibiotic therapy for EGFR inhibitors papulo-pustular rash who undergo a therapeutic switch towards immunotherapy, may have an inferior response compared to antibiotic naive patients." (PMID 34362003, 2021). "Thus, topical bucillamine is a potential reliever of irreversible EGFR-TKI-induced skin rash." (PMID 31703435, 2019). "The addition of an anti-EGFR agent to chemotherapy significantly increased some grade 3/4 toxicities including diarrhea (RR = 1.42, [95% CI, 1.03–1.94], P = 0.03), mucositis (RR = 3.30 [95% CI, 1.54–7.07], P = 0.002), and skin rash (RR = 6.82 [95% CI, 3.15–14.78], P < 0.00001)." (PMID 29228748, 2017). "Whether skin rash predicted the outcome of patients treated with EGFR TKI remains controversial." (PMID 26216071, 2015). "Thus, skin rash development has been strongly correlated with EGFR-TKI efficacy." (PMID 24661457, 2014).